MET (MET proto-oncogene, receptor tyrosine kinase)
Diseases named in the same sentence as MET in open-access papers (continued):
Sharing a sentence is not in itself a finding about the gene and the disease.
lung cancer (continued). "There are various MET alterations in lung cancer, including amplifications (1–3%) or fusions and point mutations, such as MET exon 14 skipping mutation (3–4%)." (PMID 40507907, 2025). "In lung cancer specifically, a number of patients have been identified as possessing MET alterations, commonly receptor amplification (METamp) or splice site mutations resulting in loss of exon 14 (METex14)." (PMID 39858062, 2025). "Lung cancer patients co-harboring EGFR Ex19del mutation and MET de novo amplification is extremely uncommon." (PMID 40034596, 2025). "Tobacco is a major carcinogen linked to lung cancer, but other genetic triggers, particularly mutations in KRAS, EGFR, ALK, BRAF, RET, MET and ROS1, are also central to its development." (PMID 40556802, 2025). "Tepotinib is another MET TKI that is currently being investigated, in combination with osimertinib, in patients with EGFR-mutated lung cancer who acquired MET amplification after progressing to osimertinib." (PMID 40243603, 2025). "Overall, our data demonstrate that some patients with breast and lung cancer develop polyreactive antibodies that cross-react with MET." (PMID 40401526, 2025). "Autoantibodies against the oncoreceptor MET were detected in breast and lung cancer patients, exhibiting anti-cancer effects on tumor cells along with polyreactivity and low thermostability." (PMID 40401526, 2025). "MET amplification has been proven to mediate gefitinib resistance by activating Erb‐B2 receptor tyrosine kinase 3 (ERBB3)–PI3K/Akt signaling pathway in lung cancer." (PMID 39184861, 2024). "MET fusion (TPR-MET) was initially discovered in an osteogenic sarcoma cell line, with an incidence of approximately 0.5% in lung cancer." (PMID 38472960, 2024). "We next performed the RNA-seq and KEGG pathway analysis upon MET silencing by siRNAs in H1299, H1975, and PC-9 lung cancer cell lines." (PMID 39664584, 2024). "MET pathway activation is one of the most common mechanisms of resistance to osimertinib in EGFR-mutant non–small cell lung cancer (NSCLC)." (PMID 38276867, 2024). "Concomitantly with these main targeted therapies, there are others that have already been approved by the FDA for lung cancer treatment targeting KRAS (G12C mutation), MET (exon 14 skipping), NTRK, HER2, and RET fusion." (PMID 38793028, 2024). "For example, it has been shown that METex14Del, in contrast to kinase-domain-mutated MET variants, induces sustained downstream signalling, including RAS-ERK signalling, well known to be activated in lung cancer." (PMID 38652103, 2024). "In this context, we present a case of MET-amplified intrahepatic BTC that responded to molecularly informed therapy with Tepotinib, a MET inhibitor routinely used in the treatment of MET-altered lung cancer." (PMID 39356253, 2024). "In the case of lung cancer, MET gene amplification has been identified in a subset of adenocarcinomas." (PMID 39130630, 2024). "EGFR and c‐MET gene mutations can occur in both lung and gastric cancers, and the abnormal expression of c‐MET is mainly reflected in non‐small cell lung cancer." (PMID 38770671, 2024). "Pharmacological inhibition of the MET/AKT axis reduces FOXM1 levels in lung adenocarcinoma cells, suggesting that MET/AKT is a critical target for inhibiting FOXM1 in lung cancer." (PMID 39594778, 2024). "Administering c-MET inhibitors prevented MACC1-driven cell migration in lung cancer and the induction of Akt and VEGF C/D by MACC1 in GC." (PMID 39580452, 2024). "In preclinical models of gastric and lung cancers with c-MET amplification, telisotuzumab induced tumor regression, and delayed growth, with enhanced effects combined with chemotherapeutics." (PMID 39664377, 2024).
lung cancer (continued). "In lung cancer, MET and ALK are the most commonly encountered driver genes, but they have different carcinogenic mechanisms." (PMID 39751645, 2024). "The results suggested that MET fusions, such as PTPRZ1–MET in glioma and glioblastoma cells or KIF5B-MET and EPHB4-MET in lung cancer cells, can upregulate the expression and enhance the phosphorylation of the MET protein, even without HGF stimulation." (PMID 38195556, 2024). "As such, we have established that TWIST1 is a critical downstream target of the HGF/MET pathway as it was required both in vitro and in vivo for HGF/MET-driven lung cancer." (PMID 38485737, 2024). "In conclusion, we comprehensively investigated the clinical and molecular characteristics of MET fusions in the largest lung cancer cohort to date." (PMID 37588206, 2024). "The discovery that 22% of lung cancer specimens resistant to gefitinib or erlotinib show MET amplification points to a significant mechanism of drug resistance." (PMID 39769452, 2024). "The management of lung cancer (LC) requires the analysis of a diverse spectrum of molecular targets, including kinase activating mutations in EGFR, ERBB2 (HER2), BRAF and MET oncogenes, KRAS G12C substitutions, and ALK, ROS1, RET and NTRK1-3 gene fusions." (PMID 38966170, 2024). "Deregulation of this cycle of RTK activation and recycling is often observed in cancers, such as the MET exon 14 deletions found in lung cancers." (PMID 38480916, 2024). "The mutations affecting the MET c-CBL binding site make up roughly 2% of all MET exon 14 alterations seen in lung cancer." (PMID 39130630, 2024). "Overall, based on our in vivo and patient data, we suggest a clinical pathway incorporating phospho-MET IHC staining in addition to standard MET FISH assays to guide treatment for patients with osimertinib-resistant EGFR-mutant lung cancer." (PMID 38276867, 2024). "Common genetic mutations in lung carcinoma include EGFR, KRAS, EML4-ALK, Ros1, and c-MET, among others." (PMID 38571504, 2024). "In this study, we revealed the different mechanisms of acquired resistance to the MET inhibitor crizotinib with potential therapeutic application in patients with MET-amplified lung carcinoma." (PMID 38758826, 2024). "Wang and his/her colleagues reported a case of lung cancer with both MET gene amplification and KLC1-ALK fusion, this patient had a good response to Crizotinib." (PMID 37658352, 2023). "Recently, a series of reports revealed novel detectable alterations of MET, MET fusions, which are involved in the development of lung cancer and exhibit a special response to the given treatment." (PMID 36829199, 2023). "Patients with advanced MET 14 exon alterations in lung cancer show a long‐lasting response to MET inhibitors." (PMID 38077251, 2023). "In particular, they found that these EGFR-mutant lung cancer cell lines mainly acquired MET amplification as a mechanism of resistance and become sensitive to afatinib plus crizotinib." (PMID 37152062, 2023). "Tepotinib is currently approved for the treatment of adult patients with advanced or metastatic non–small cell lung cancer harboring MET exon 14 skipping alterations." (PMID 36999986, 2023). "Since circulating MET ectodomain shedding is also reported in preclinical cancer cell models and lung cancer patients, how soluble MET shedding would influence MET-CAR-T cell efficacy needs to be evaluated when MET-CAR-T cells enter clinical trials." (PMID 37779207, 2023). "Multiple concomitant genomic alterations were detected in lung cancer patients harboring MET fusions, but concomitant MET amplifications (35.7%) seemed to be the most common genomic alteration." (PMID 36829199, 2023). "Another well-studied receptor tyrosine kinase is called MET, which has been an important therapeutic target in lung cancer." (PMID 37345192, 2023).
lung cancer (continued). "Consistently, in the in vivo xenograft model, compared to control mice, mice bearing MET-amplified EBC-1 lung cancer cells with stable SYK knockdown exhibited a significantly reduced response to the c-Met inhibitor INCB28060." (PMID 37183231, 2023). "Overall, the Ion AmpliSeq Colon and Lung Cancer Research Panel v2, improved with three additional amplicons to cover exon 14 and its surrounding introns, enabled an increased detection rate of MET exon 14 skipping molecular alterations." (PMID 36832117, 2023). "To determine what kind of therapeutics would benefit lung cancer patients harboring MET fusions, we performed a literature review of cases published by September 2022." (PMID 36829199, 2023). "In lung cancer, we and other groups reported that activation of HGF/MET causes resistance to EGFR‐TKIs and ALK‐TKIs in EGFR‐mutated NSCLC and ALK‐rearranged NSCLC, respectively." (PMID 36416133, 2023). "In lung cancer, oncogenic MET gene activation can happen through two mechanisms: exon 14 skipping mutations or MET gene amplification." (PMID 37509393, 2023). "Another study reported that long noncoding RNA Linc00857 interacting with YBX1 to regulate autophagy and proliferation of lung cancer cells through MET proto-oncogene (MET)/AMPK signaling." (PMID 36642732, 2023). "In the two databases involved in this study, MET fusions were rare in lung cancer patients, being found in 0.2% (56/30876, LAVA database) to 0.3% (22/7966, the cBioPortal database) of all patients." (PMID 36829199, 2023). "Amivantamab is a human monoclonal IgG1 antibody that targets both EGFR and MET, which are involved in driving tumor growth in lung cancer and activation of the MET pathway through the positive regulation of MET expression." (PMID 37895255, 2023). "METex14 lung cancer cell line models were established using CRISPR technology, where deletion of MET exon 14 in both alleles was regarded as mutated (METex14), and cell lines with intact MET exon 14 were used as wildtype." (PMID 37444481, 2023). "Combining EGFR inhibition and MET inhibition showed anticancer activity in EGFR‐TKI‐resistant MET‐amplified lung cancers in clinical trials." (PMID 38140788, 2023). "Considering the relatively high frequency of MET alterations in lung cancers with EGFR mutations, co-targeting EGFR and MET with either a kinase inhibitor or an antibody appears to be a logical therapeutic strategy that is currently being evaluated." (PMID 37894376, 2023). "In vitro, in EBC-1 lung cancer cells harboring high-level METamp, tepotinib potently inhibited MET phosphorylation (IC50 = 1.1 nmol/L), as measured using a capture Enzyme-linked Immunosorbent Assay." (PMID 36999986, 2023). "For example, MET fusions have been identified in various types of cancer such as osteosarcoma, gastric cancer, thyroid cancer, lung cancer, glioma, and sarcoma." (PMID 38077251, 2023). "MET fusions were found in only 0.2% to 0.3% of lung cancer patients and appeared in almost all exons of the MET gene." (PMID 36829199, 2023). "Amplifications of MET allow targeting with specific tyrosine kinase inhibitors, which has proven successful in lung cancer patients." (PMID 37620318, 2023). "Targeted inhibition of the MET/PI3K/AKT signaling pathway enhances the sensitivity of lung cancer cells to EGFR inhibitors." (PMID 38115126, 2023). "Further, through thousands of protein screenings, we identified four proteins (MYH9, GNB1, ALOX12B, HSD17B4) that can predict the response to MET inhibitors for MET-dysregulated lung cancer patients." (PMID 36612298, 2023).
lung cancer (continued). "Cabozantinib, a small molecule multi-tyrosine kinase inhibitor against vascular endothelial growth factor receptor (VEGFR) and MET was used in patients with MET amplification, as it was shown to be effective in the treatment of lung cancer." (PMID 35953681, 2023). "For example, MET activation, another cause of EGFR TKIs resistance in lung cancer, can promote drug resistance by reactivating PI3K/AKT and MEK/ERK signaling pathways in the presence of EGFR inhibition." (PMID 37638338, 2023). "It was previously demonstrated that in non‐small cell lung cancer cells, MET overexpression upregulated EGFR downstream signalling and the use of both EGFR/HER2 and MET tyrosine kinase inhibitors led to a maximal growth inhibition." (PMID 37679999, 2023). "Previous studies have confirmed that MET expression is active in various cells of tumors, such as lung cancer, brain cancer and glioma, which is closely related to the growth and proliferation of tumor cells." (PMID 36502446, 2022). "In this way, miR-206 regulates MET protein in A-549 lung cancer cells by directly targeting MET 3′-UTR and activated MET/PI3K/Akt/mTOR signaling pathway to induce DDP resistance (Chen QY." (PMID 35444536, 2022). "At present, studies have confirmed that MET expression is active in various tumor cells, such as lung cancer and glioma, and is closely related to the growth and proliferation of tumor cells." (PMID 36502446, 2022). "In another genomic study of BM of various origin, several potentially actionable genomic alterations were associated with lung cancer BM, including AKT1, AURKA, CDK6, EGFR, MEK1, MET, and PIK3CA gene amplifications and CDKN2A deletions." (PMID 36561283, 2022). "Targeted therapies for MET exon 14-skipping (METΔex14)-driven lung cancers have generated some promising results but response rates remain below that seen for other kinase-driven cancers." (PMID 35326531, 2022). "Lung cancers with MET amplifications were resistant to ICB therapy through decreasing STING levels and antitumor T cell infiltration." (PMID 36201246, 2022). "For lung cancers, lung adenocarcinomas baring mutations in EGFR, KRAS, ERBB2, and MET are reported to also host a higher number of “rearrangements”34." (PMID 35710642, 2022). "Among them, compound CM9 bearing p-bromo benzyl pendant on the triazole ring exhibited the highest MET inhibitory activity and anti-proliferative effects towards MET-amplified lung cancer cells." (PMID 36465863, 2022). "Two oral small-molecule multi-kinase inhibitors with activity against c-MET: cabozantinib and crizotinib, are effective in renal, thyroid and lung cancer." (PMID 35144591, 2022). "For example, in the anti-EGFR target therapy using gefitinib for lung cancer, MET (receptor of HGF) amplification leads to resistance by activating ERBB3 signaling." (PMID 35625759, 2022). "MET amplification has been observed in lung cancer patients treated with the EGFR inhibitors gefitinib and erlotinib, and treatment of gefitinib-resistant tumors with the Met inhibitor crizotinib is effective in the clinic for these patients." (PMID 35249128, 2022). "First, MET amplification has been shown to result in constitutive activation of ERBB3 signaling to promote gefitinib resistance in lung cancer cell lines." (PMID 34675407, 2022). "MET exon 14 (METex14) alteration occurs with low frequency in stomach (4.8–7.1%), colorectal (~0–9.3%), and lung cancers (adenocarcinoma, 2.6–3.2%; pulmonary sarcomatoid tumor, 2.6–31.8%; adenosquamous carcinoma, 4–8.2%)." (PMID 35884507, 2022). "Recent studies indicate that amplification of MET is a druggable genetic mechanism of resistance in RET fusion–positive lung cancer." (PMID 35510953, 2022). "HGF also encourages the phosphorylation of c-MET, thus facilitating the generation of gefitinib resistance in lung cancer." (PMID 36359776, 2022).
lung cancer (continued). "Compound CM9 showed antiproliferative effect against cancer cells, in particular lung cancer cells with MET amplification (EBC-1) with an IC50 value of 8.6 μM." (PMID 36465863, 2022). "KRAS amplification contributes to the resistance to MET inhibition in lung cancer, and MET amplification was noticed in the acquired resistance to the KRAS G12C inhibitor." (PMID 36230855, 2022). "We firstly screened the EGFR and MET signaling, which are the most important pathways in lung cancer progression by Western blot." (PMID 35635086, 2022). "Until recently, MET fusion, such as KIF5B-MET, MET-ATXN7L1, and HLA-DRB1-MET had mainly been reported in lung cancer." (PMID 36483096, 2022). "The coexistence of ALK, MET, and other alterations has been observed in a series of cases with lung cancer and is reported here in MET-positive ASPS tumors with ALK mutations." (PMID 35628499, 2022). "c-Met signaling regulates the expression the PEA3 factors to promote cell migration and invasion in gastric and lung cancer cells with MET-addicted." (PMID 36109787, 2022). "A total of three (0.02%) lung cancer patients harbored MET fusions, against which crizotinib has reportedly demonstrated clinical activity." (PMID 36369474, 2022). "In osimertinib-resistant lung cancer cell lines harboring T790M mutation that we established, expression of multiple EGFR family proteins and MET was markedly reduced, whereas expression of AXL, CDCP1 and SRC was augmented along with activation of AKT." (PMID 35643725, 2022). "More importantly, they also used clinical specimens to show that MET gene amplification was detected in 4 of 18 (22%) of the lung cancer specimens that had developed AR to gefitinib or erlotinib." (PMID 33572269, 2021). "Most knowledge on the correlation between MET-gene copies and MET signaling in cancer patients derives from investigations in lung cancer." (PMID 34884673, 2021). "In order to further explore the impact of the HGF/c-MET pathway on tumors, we conducted some experiments in vitro in lung cancer and esophageal cancer cell lines." (PMID 34261467, 2021). "Here, we identify and characterize six patient-derived models of EGFR-mutant, MET-amplified lung cancer that have switched oncogene dependence to rely exclusively on MET activation for survival." (PMID 34516823, 2021). "Therapies with c-MET-TKIs (e.g., crizotinib, cabozantinib) have proven beneficial in lung cancer patients with MET gene amplification, preventing tumor growth, proliferation, and dissemination." (PMID 34504652, 2021). "Effective therapies have been currently developed to target EGFR, KRAS, and MET; however, the prognosis of patients with advanced lung cancer remains unsatisfactory." (PMID 33981850, 2021). "Transfer of EVs derived from icotinib-resistant lung cancer cells into icotinib-sensitive lung cancer cells induced the expression of MET, which plays a role in migration." (PMID 34527665, 2021). "Extensive evidence has suggested that the HGF/MET signaling pathway is essential in lung cancer tumorigenesis and progression via the alteration of cell apoptosis, growth, migration and morphology." (PMID 33917539, 2021). "This demonstrated that EGFR/MET tumors are resistant to osimertinib, mimicking what is observed in EGFR-mutated lung cancer patients with MET amplification." (PMID 34298655, 2021). "Savolitinib, a potent, selective MET TKI, plus osimertinib are undergoing trials to determine their effect on EGFR mutation-positive lung cancers with MET amplification." (PMID 34677235, 2021). "It was demonstrated that c-MET-GRB2 protein complex abundance predicts c-MET survival signaling and correlates with sensitivity to c-MET inhibitors in c-MET-driven cellular models of lung cancer." (PMID 34490234, 2021). "Mechanistic studies have shown that METTL3 combines with MET and causes the PI3K/AKT signalling pathway to be manipulated, which affects the sensitivity of lung cancer cells to gefitinib." (PMID 33491264, 2021).